TBX3 (T-box transcription factor 3)
Diseases named in the same sentence as TBX3 in open-access papers (continued):
Sharing a sentence is not in itself a finding about the gene and the disease.
gastric cancer (2 papers, 2022). A primary or metastatic malignant neoplasm involving the stomach. "Studies have also shown that the over-expression of TBX3 (a member of the T-box transcription-factor family) in human gastric cancer tissue was associated with the advanced stage of tumors and lymph node status and contributes to the growth and invasion of cancer cells." (PMID 35847930, 2022). "In the current study, we assessed the expression of TBX3 in human gastric tissues and found that the expression of TBX3 was increased in precancerous atrophic gastritis and even more increased in gastric cancer tissues." (PMID 36923312, 2022). "This TBX3 expression was observed in human atrophic gastritis and its expression was even more enhanced in gastric cancer tissues." (PMID 36923312, 2022). "This, together with the induced Tbx3 and suppressed Dkk3, suggested that the aged gastric organoids in the current study possibly possessed the potential to develop gastric cancer." (PMID 36923312, 2022). "On the other hand, DKK3 showed a reciprocal expression to TBX3 (2.20 ± 0.06 in oxyntic glands, 1.75 ± 0.06 in atrophic gastritis, 0.52 ± 0.14 in gastric cancer)." (PMID 36923312, 2022). "Because the enhanced Tbx3 expression seen in aged gastric organoids was also observed in human gastric cancer tissues, this Dkk3-Wnt-Tbx3 pathway may be involved in aging-related gastric carcinogenesis." (PMID 36923312, 2022). "On the other hand, most of the gastric cancer cells expressed TBX3 (69.18% ± 5.53%)." (PMID 36923312, 2022). "Finally, the expression of TBX3 was enhanced in human atrophic gastritis and even more enhanced in human gastric cancers." (PMID 36923312, 2022).
glioblastoma (2 papers, 2017 to 2024). The most malignant astrocytic tumor (WHO grade IV). "Recently, these drugs have demonstrated efficacy in inhibiting TBX3 expression in glioblastoma cells, thus limiting cell viability." (PMID 38673810, 2024).
Inguinal hernia (2 papers, 2019 to 2025). Protrusion of the contents of the abdominal cavity through the inguinal canal. "Genetic studies from China revealed that DNA sequence variants (DSVs) might contribute to inguinal hernia development by changing the transcriptional activities of TBX1, TBX2, TBX3, Sirtuin 1, and GATA transcription factor 6 (GATA6) gene promoters." (PMID 31024927, 2019).
Insulin resistance (2 papers, 2022 to 2025). Increased resistance towards insulin, that is, diminished effectiveness of insulin in reducing blood glucose levels. "For example, miR‐93 has been shown to control adipocyte differentiation by negatively regulating Tbx3, and loss of miR‐93 results in increased fat mass and insulin resistance." (PMID 36062491, 2022). "Loss of miR‐93 can increase adipose cell differentiation, fat mass, and subsequently insulin resistance by targeting Tbx3 gene." (PMID 36062491, 2022). "Overall, these results show that Tbx3 loss alone is insufficient to drive insulin resistance, making complete insulin resistance unlikely to be responsible for MASLD protection." (PMID 40638249, 2025). "Surprisingly, Tbx3-KO mice exhibited increased glucose intolerance, fasting hyperinsulinemia, and increased plasma triglycerides and non-esterified fatty acids, all of which indicated increased insulin resistance." (PMID 40638249, 2025). "While selective insulin resistance seen in diabetic patients is a major driver of fatty liver disease, complete loss of hepatic insulin signaling is known to ameliorate MASLD, so we asked whether Tbx3 might induce complete insulin resistance." (PMID 40638249, 2025). "Tbx3 loss does not improve fatty liver through altered insulin resistance." (PMID 40638249, 2025). "Because insulin resistance is correlated with MASLD progression, we asked whether Tbx3-KO mice were protected from MASLD through altered insulin sensitivity." (PMID 40638249, 2025).
invasive breast carcinoma (2 papers, 2016 to 2019). A carcinoma that infiltrates the breast parenchyma. "We confirmed an association between TBX3 and estrogen receptor (ER) and progesterone receptor (PR) expression in invasive breast cancers, which has been suggested by previous studies." (PMID 30697731, 2019). "Our first cohort consisted of 186 pre‐invasive (stage 0, DCIS only) and early invasive breast cancer (IMC; invasive mammary carcinoma, stage I) patient samples, where we used an antibody that recognizes both TBX3 isoforms." (PMID 30697731, 2019). "By using the 21T cell line series to model the effects of putative drivers of the transition from pre-invasive to invasive breast cancer progression, we are able to demonstrate that overexpression of TBX3 can promote the transition of DCIS to IMC." (PMID 27553211, 2016). "In addition, TBX3 expression was knocked down to evaluate the effects of downregulating TBX3 on the invasive mammary carcinoma-like 21MT-1 cell line." (PMID 27553211, 2016).
invasive carcinoma (2 papers, 2019 to 2020). A carcinoma that is not confined to the epithelium, and has spread to the surrounding stroma. "By utilizing a nude mouse xenograft model, we have identified differential tumorigenic potential between TBX3 isoforms, with TBX3iso1 overexpression more commonly associated with invasive carcinoma and high tumor vascularity." (PMID 31570773, 2020). "Through nude mouse xenograft experiments utilizing non-tumorigenic 21NT cell lines, we have reported significant differences between TBX3 isoforms in the promotion of tumorigenesis, with TBX3iso1 overexpression more commonly associated with initiation and progression of invasive carcinoma in vivo." (PMID 31570773, 2020). "In conclusion, we propose a unique pathway in which TBX3 promotes progression through advancement of low‐grade DCIS to invasive carcinoma." (PMID 30697731, 2019). "Importantly, we observed differential tumorigenicity between TBX3 isoforms when expressed in non-tumorigenic 21NT breast epithelial cells, with TBX3iso1 associated with invasive carcinoma and high tumor vascularity." (PMID 31570773, 2020). "By utilizing a nude mouse xenograft model, the authors identified differential tumorigenic potential between TBX3 isoforms, with TBX3iso1 (but not TBX3iso2) promoting invasive carcinoma in vivo through induction of angiogenesis." (PMID 31570773, 2020). "Additionally, there was a positive correlation between TBX3 and SLUG, and TBX3 and TWIST1 in the invasive carcinoma." (PMID 30697731, 2019).
neuroblastoma (2 papers, 2021 to 2024). Neuroblastoma (NB) is the most common solid, extracranial childhood tumor. "Thus, ATRA initiates a change in cell state of neuroblastoma cells corresponding to a shift from the adrenergic CRC to a new retino-sympathetic CRC, which includes RARA, HAND2, ISL1, TBX2, TBX3, MEIS1, and SOX4." (PMID 34669465, 2021).
prostate tumor (2 papers, 2016 to 2025). "Furthermore, impaired growth andproliferation of prostate tumor cells was observed for bothHOXB13 and TBX3 using two depletion methods: knockout(CRISPR) and knockdown (RNAi)." (PMID 41164275, 2025).
steatosis (2 papers, 2023 to 2025). Increased lipid within the cytoplasm of cells. "While female mice develop less MASLD than male mice, Tbx3-KO females still showed reduced steatosis." (PMID 40638249, 2025). "Surprisingly, knockout of Tbx3 (transcription factors) and Smyd2 (epigenetic factor) resulted in the most significant reduction of liver injury and steatosis, even though Tbx3 and Smyd2 have not been linked to NAFLD/NASH pathogenesis before." (PMID 37620333, 2023).
acute pancreatitis (1 paper, 2023). An acute inflammatory process that leads to necrosis of the pancreatic parenchyma. "Since pancreatic development shares common regulatory patterns with pancreatic repair, we challenged Tbx3-KO (epi) mice and control mice with caerulein-induced acute pancreatitis to investigate the potential relevance of Tbx3 under exogenous stress conditions." (PMID 36941669, 2023). "Although Tbx3 seems dispensable for proper pancreatic development and lineage entry, its absence results in altered organ regeneration after induction of acute pancreatitis marked by enhanced fibrosis and inflammation." (PMID 36941669, 2023). "Although TBX3 is dispensable for proper pancreatic development, its absence leads to altered organ regeneration after induction of acute pancreatitis." (PMID 36941669, 2023). "TBX3 shows switching expression patterns during embryonic development in the pancreas and leads to fine-tuning of regeneration from acute pancreatitis via limiting proliferation and fibrosis during regeneration." (PMID 36941669, 2023). "Driven by the fact that developmental programs can become re-activated during regeneration from injury, we investigated the relevance of Tbx3 for regeneration after caerulein-induced acute pancreatitis." (PMID 36941669, 2023). "In an adult model of acute pancreatitis, we found that a lack of Tbx3 resulted in increased proliferation and fibrosis as well as an enhanced inflammatory gene programs, indicating that Tbx3 has a role in tissue homeostasis and regeneration." (PMID 36941669, 2023). "Even though we did not observe a gross impact of Tbx3 on recovery from acute pancreatitis, we observed (i) higher amounts of fibrosis, (ii) prolonged proliferation in acinar cells in its absence, and (iii) higher variance in some investigated parameters of regeneration of Tbx3-KO mice." (PMID 36941669, 2023).
Arrhythmia (1 paper, 2023). Any cardiac rhythm other than the normal sinus rhythm. "Additionally, several studies have shown that both pre- and postnatal loss of Tbx3 results in arrhythmia predisposition, while signaling upstream Tbx3 leading to reduced Tbx3 expression leads to loss of AV-junctional cell identity." (PMID 38201209, 2023).
Arthritis (1 paper, 2019). Inflammation of a joint. "We showed that a small genetic fragment on mouse chromosome 5, including Tbx3 and three additional protein-coding genes, is linked to severe arthritis and high titers of anti-collagen antibodies." (PMID 30630509, 2019). "In the current study, we showed that B10.RIIIS/J-Eae39r2 sub-congenic mice (with Tbx3, Tbx5 and Rbm19 in the sub-congenic fragment) develop more severe arthritis compared to the control mice." (PMID 30630509, 2019). "We have fine-mapped the CIA enhancing Eae39r locus and suggest that the therein located Tbx3 gene is a disease candidate gene for experimental arthritis in the mouse." (PMID 30630509, 2019). "Furthermore, our preliminary data show that TBX3 is a putative RA biomarker and that an increase in TBX3 serum levels in untreated arthritis reflects dysregulation of currently unidentified disease pathways." (PMID 30630509, 2019). "Moreover, we observed that serum levels of TBX3 follow arthritis severity." (PMID 30630509, 2019).
atrophic gastritis (1 paper, 2022). "In the atrophic gastritis cases, it was also expressed in the isthmus, and due to the elongation of the isthmus, there were more TBX3 positive cells in atrophic gastritis tissues compared with the oxyntic gland tissues (26.06% ± 2.20%)." (PMID 36923312, 2022).
autoimmune disease (1 paper, 2019). A disorder resulting from loss of function or tissue destruction of an organ or multiple organs, arising from humoral or cellular immune responses of the individual to their own tissue constituents. "Taken together, these results indicate that TBX3 is involved in RA pathogenesis and possibly also in other autoimmune diseases dependent on B cell activation and autoantibody production." (PMID 30630509, 2019).
chronic obstructive pulmonary disease (1 paper, 2020). A chronic and progressive lung disorder characterized by the loss of elasticity of the bronchial tree and the air sacs, destruction of the air sacs wall, thickening of the bronchial wall, and mucous accumulation in the bronchial tree. "Downregulated expression levels of SIRT1 and TBX-3 have also been observed in lung specimens derived from chronic obstructive pulmonary disease, which indicated that SIRT1 and TBX-3 are not always negatively regulated." (PMID 32627000, 2020).
colon adenocarcinoma (1 paper, 2025). "TBX3 was significantly overexpressed in BLCA, colon adenocarcinoma (COAD), esophageal carcinoma (ESCA), and rectum adenocarcinoma (READ)." (PMID 39897553, 2025).
Cousin Syndrome (1 paper, 2010). "In digit formation specifically, Tbx3 is thought to modulate posterior digit identity through Shh and BMP signaling, and Tbx15 insufficiency causes Cousin Syndrome which includes congenital dwarfism, moderate brachydactyly (or shortening of the digits) and leg shortening." (PMID 21054883, 2010).
diabetes (1 paper, 2020). "The present study demonstrated that TBX-3 expression levels were increased in patients with diabetes compared with normal recruited controls." (PMID 32627000, 2020). "Similarly, the expression levels of TBX-3 were identified to be significantly upregulated in the serum of 15 patients with diabetes compared with normal participants." (PMID 32627000, 2020). "Subsequently, a positive correlation was observed between SIRT1 and TBX-3 mRNA expression levels in the serum of patients with diabetes (R=0.710; P<0.001), suggesting that SIRT1 may positively regulate TBX-3 in endothelial cells." (PMID 32627000, 2020).
embryonal cancers (1 paper, 2022). A non-seminomatous malignant germ cell tumor characterized by the presence of large germ cells with abundant cytoplasm resembling epithelial cells, geographic necrosis, high mitotic activity, and pseudoglandular and pseudopapillary structures formation. "PI3K/AKT/TBX3 axis plays an important role in maintaining pluripotency of mouse ES cells and it has been reported as a treatment target in multi type of embryonal cancers." (PMID 35610614, 2022). "Furthermore, PI3K/AKT/TBX3 axis which was included in “Signaling pathways regulating pluripotency of stem cells” plays an important role in maintaining pluripotency of mouse ES cells and it has been reported as a treatment target in multi-type of embryonal cancers." (PMID 35610614, 2022).
endothelial dysfunction (1 paper, 2020). In vascular diseases, endothelial dysfunction is a systemic pathological state of the endothelium (the inner lining of blood vessels) and can be broadly defined as an imbalance between vasodilating and vasoconstricting substances produced by (or acting on) the endothelium. "Given the significance of this transcription factor and its modifications over the expression levels of its target genes in the normally quiescent endothelial cells, the present study aimed to investigate whether TBX-3 had a role in mediating endothelial dysfunction and its associated vasculopathy." (PMID 32627000, 2020). "In addition, the study further determined the molecular pathways of TBX-3-mediated endothelial dysfunction." (PMID 32627000, 2020). "The present study aimed to investigate the role of sirtuin 1 (SIRT1)- and transcription box-3 (TBX-3)-mediated regulation of endothelial dysfunction, given the significance of SIRT1 in glucose metabolism and the role of TBX-3 in the maintenance of cellular proliferation, senescence and apoptosis." (PMID 32627000, 2020).
gestational diabetes (1 paper, 2020). Carbohydrate intolerance first diagnosed during pregnancy. "The differences in the mRNA expression levels of TBX-3 in primary endothelial cells from the umbilical cord vein between women with gestational diabetes and normal women was investigated." (PMID 32627000, 2020).
glioma (1 paper, 2020). A benign or malignant brain and spinal cord tumor that arises from glial cells (astrocytes, oligodendrocytes, ependymal cells). "In this study, TBX3 is a protective factor in IDH-wildtype but a risk factor in IDH-mutation 1p/19q codeletion gliomas." (PMID 32489448, 2020).
Hernia (1 paper, 2025). "In this context, we aimed to investigate the expression levels of GATA6 and TBX3 in hernia sacs obtained from patients with IIH and in prepuce tissues from circumcised healthy boys in our study population." (PMID 40622564, 2025). "The aim of the study is to examine the expression levels of the GATA6 and TBX3 genes in hernia sacs from patients with indirect inguinal hernia (IIH) in the Trakya region, Türkiye and shed light on the etiology of this common surgical disease in childhood." (PMID 40622564, 2025).
Hyperglycemia (1 paper, 2020). An increased concentration of glucose in the blood. "Therefore, the present study also aimed to determine whether the expression levels of TBX-3, the gene coding for TBX-3, were upregulated in endothelial cells in response to hyperglycemia, in addition to their contribution to the neotransformation of cells." (PMID 32627000, 2020).
hyperlipidemia (1 paper, 2025). "In conclusion, TBX3 mutant clones expand during MASLD through increased lipid disposal, demonstrating that clonal fitness can benefit the liver at the cost of hyperlipidemia." (PMID 40638249, 2025).
hyperthyroidism (1 paper, 2023). Overactivity of the thyroid gland resulting in overproduction of thyroid hormone and increased metabolic rate. "In the present case, even though the child had hyperthyroidism; because he displayed increased thyroid autoimmune antibodies, it can be considered as immune thyroiditis and not a result of TBX3 mutation." (PMID 36937985, 2023).
hypogonadotropic hypogonadism (1 paper, 2023). Abnormal ovarian or testicular function due to insufficient hormonal stimulation from the hypothalamic-pituitary axis. "Therefore, TBX3 mutations can cause pituitary gland hypoplasia, resulting in hypogonadotropic hypogonadism (HH)." (PMID 36937985, 2023).
intrahepatic cholangiocarcinoma (1 paper, 2024). A carcinoma that arises from the intrahepatic bile duct epithelium in any site of the intrahepatic biliary tree. "However, TBX3 function remains undetermined in intrahepatic cholangiocarcinoma (iCCA), a deadly primary liver malignancy with few systemic treatment options." (PMID 38909034, 2024).
invasive lobular carcinomas (1 paper, 2020). "Recently, molecular analyses of invasive lobular carcinomas established that these tumors have a distinct genomic profile compared to IBC-NST, exhibiting a high frequency of CDH1 mutations, loss of PTEN, activation of AKT, and mutations in TBX3 and FOXA1." (PMID 32487046, 2020).
liver disease (1 paper, 2025). "TBX3 somatic mutations were identified in the livers of patients with metabolic dysfunction-associated steatotic liver disease, and loss of Tbx3 in mouse hepatocytes leads to clonal expansions." (PMID 40638249, 2025).
liver fibrosis (1 paper, 2025). "Tbx3-KO mice also had similar levels of plasma ALT and AST, as well as similar levels of liver fibrosis." (PMID 40638249, 2025).
lung squamous cell carcinoma (1 paper, 2024). "Then we used Human Protein Atlas to determine the expression of TBX2, TBX3, TBX4 and TBX5 in lung squamous cell carcinoma tissues." (PMID 38413457, 2024).
mesenchymal tumors (1 paper, 2024). "Because strategies aimed at reactivating TBX3 in iCCA lesions might be harmful due to the risk of inducing mesenchymal tumors, TBX3 downstream targets whose inactivation is detrimental to biliary tumorigenesis should be unraveled." (PMID 38909034, 2024). "Interestingly, TBX3 overexpression can cause the development of mesenchymal tumors with osteoid differentiation in a subset of these mice." (PMID 38909034, 2024).
neurofibroma (1 paper, 2024). An intraneural or extraneural neoplasm arising from nerve tissues and neural sheaths. "Additionally, transcription factors such as FOXC1, which has been associated with the development of multiple tumors, TBX3, associated with Ulna-Mamma Syndrome, and TEAD1, linked to Neurofibroma and Spindle Cell Rhabdomyosarcoma, could be considered targets for drug repositioning." (PMID 38673810, 2024).
ovarian tumor (1 paper, 2022). "Gain of function (GoF) mutations were identified in PIK3CA and TBX3 in one breast and one ovarian tumor, respectively." (PMID 36344544, 2022).